SMAD2 (SMAD family member 2)
Diseases named in the same sentence as SMAD2 in open-access papers (continued):
Sharing a sentence is not in itself a finding about the gene and the disease.
tumor (continued). "TEFT inhibits GBM progression by suppressing the TGF‐β/SMAD2/3/STAT3/C1R axis, thereby attenuating EMT and reducing tumor aggressiveness." (PMID 41489302, 2026). "Mechanistically, NPY activated ERK and Smad2 via NPY1R, synergising with TGFβ signalling in tumour cells expressing TβRI." (PMID 41298817, 2025). "SMAD2/3 phosphorylation is a key downstream event in TGF-β-induced EMT, leading to transcriptional changes that promote tumor progression." (PMID 40134588, 2025). "TAM M2 can activate Smad2/3 and Smad1/5/8, thereby promoting the epithelial–mesenchymal transition (EMT) and tumor metastasis." (PMID 40299539, 2025). "By interacting directly with NSCLC cell Smad family members (Smad2, Smad3, and Smad4), MELK inhibits EMT and increases tumor cell motility, invasion, and metastasis." (PMID 40925573, 2025). "Multiplex immunohistochemistry performed on CRC tissue microarrays revealed increased expression of TGF-β1, TGFBRI, TGFBRII, SMAD4, SMAD2/3, SMAD1/5/9, and phosphorylated SMAD2/3 in tumor tissue compared to adjacent mucosa." (PMID 40806457, 2025). "In normal cells and early tumor stages, TGF-β acts as a tumor suppressor via the classical SMAD2/3 (small mothers against decapentaplegic) pathway." (PMID 40867239, 2025). "GDF15 modulates tumor progression through PI3K/AKT, MAPK/ERK, and SMAD2/3 signaling, thereby promoting epithelial-to-mesenchymal transition, metastasis, immune evasion, and chemoresistance via Nrf2 stabilization and oxidative stress regulation." (PMID 40868185, 2025). "In this study, we aimed to clarify the clinicopathologic significance of periostin and Smad2/3 expression in CRC, with a particular focus on the tumor microenvironment." (PMID 39941916, 2025). "TGF‐β suppresses chemokine receptor CXCR3 transcription by SMAD2/3 and thereby limiting CD8+ T‐cell trafficking to the tumor." (PMID 39083441, 2025). "We investigated the abundance of phospho-SMAD2 linker positive (pSMAD2L+) cells in NSCLC and tumour-free tissues by using a 4-plex mIF panel to discriminate epithelial cells (panCK+) and immune cells (CD45+) as well as their mitotic status, indicated by pHH3." (PMID 40319202, 2025). "Inhibition of ENG expression on myCAFs not only suppressed the TGF‐β–Smad2/3 pathway and TGF‐β1 expression but also attenuated the ability of myCAF to promote primary tumor growth and metastasis." (PMID 40644310, 2025). "Our data point to a mechanism involving dysregulation of a broad range of oncogenes such as MYC and tumour-suppressing genes such as TGF-βR2 and SMAD2/3." (PMID 39789354, 2025). "Both tumor cells and infiltrating macrophages secrete high levels of transforming growth factor-β (TGF-β), which bind TGFBR1/2 and triggers phosphorylation of Smad2/3." (PMID 40958866, 2025). "To further investigate the effect of BC tumor cells on SMAD signaling, we performed immunostaining for phosphorylated SMAD2 (p-SMAD2) in in vitro differentiated WT OCs treated with 10% CM derived from 4T1 or MDA cells." (PMID 41249489, 2025). "Taken together these results show that miR-590-3p is a potent inhibitor of SMAD2/3 signaling in Mes-like GBM cells and predicts significant anti-tumor effects in rGBM models." (PMID 40301302, 2025). "By identifying a TGF-β1/TAK1/NF-κB/SMAD2 signalling pathway triggered in NB cells by their interaction with TAM and MSC/CAF, our data brings a new insight into the contribution of TGF-β1 to tumour progression and therapeutic resistance in this cancer." (PMID 38806726, 2024). "CHI3L1 has the potential to enhance tumor growth and migration by interacting with TGF-β1 and TGFR, which subsequently activates the SMAD2/SMAD3 signaling pathway." (PMID 38177294, 2024). "MiR-132 acts as a tumor suppressor inhibited the migration and invasion of cancer cells through TGF-β1/Smad2/3 signals significantly." (PMID 38603722, 2024). "Our data point to a mechanism involving dysregulation of a broad range of oncogenes such as MYC, and tumor suppressing genes such as TGF-βR2 and SMAD2/3." (PMID 38410440, 2024).
tumor (continued). "In B-NHL, Galunisertib enhances the antiproliferative and pro-apoptotic effects of doxorubicin and further inhibits tumor growth by upregulating p-P38 MAPK and inhibiting the TGF-β/Smad2/3 and PI3K/AKT signaling pathways." (PMID 39534084, 2024). "As the marker of exhaustive CD8 T cells, HAVCR2 regulates EMT by crosstalking Akt/GSK-3β/Snail signaling pathway with SMAD7/SMAD2/ SNAIL1 Axis, implicating the dual role of Community 1-related immune genes in EMT and tumor immune." (PMID 38331768, 2024). "The KEGG biological term enrichment analysis of the mRNAs of this subnetwork revealed biological pathways associated with cell proliferation and differenciation involving the tumor suppressor genes APC and SMAD2." (PMID 38302900, 2024). "In nHM tumours, most driver genes, particularly SMAD4, SMAD2 and FBXW7, correlated with high hypoxia." (PMID 39112715, 2024). "The result of the MOC1 cell line was also consistent with that in the SCC-15 cell line and showed that both TGFβ-SMAD2 signaling and PD-L1 upregulated in MOC1 cells in the neuron-tumor coculture system." (PMID 38324026, 2024). "Glabridin inhibits the TGF-β/SMAD2 pathway by upregulating miR-148a, reducing cancer stem cell markers (CD44, EpCAM), and impairing self-renewal, tumor sphere formation, and independent growth." (PMID 39723390, 2024). "Subsequently, MMA has also been confirmed in vivo to increase the expression of INHBA, Ki-67, p-Smad2, p-Smad3, and EMT markers, according to immunohistochemistry, immunofluorescence, and western blotting assays of subcutaneous tumor tissues." (PMID 38252148, 2024). "Further, immunohistochemical (IHC) analysis of tumor tissues confirmed that the combination of α-hederin and PTX significantly decreased the expression of SREBF1, FASN, phosphorylated SMAD2, and the sEVs-marker protein TSG101 compared to PTX alone." (PMID 38362150, 2024). "Navigating through the nuanced cellular machinations within the tumor microenvironment (TME), this study unearthed pivotal insights elucidating TGF-β’s capability to augment LIF expression, activated via the Smad2/3 complex." (PMID 38490994, 2024). "By competing with SMAD2 (Recombinant Mothers Against Decapentaplegic Homolog 2) and modifying the TGF pathway’s activity, MIR22HG was able to exhibit its tumor suppressor effect." (PMID 38110999, 2023). "In tumor tissues of nude mice co-injected with M2-TAMs and EC109 cells, p-Smad2/3 protein levels likewise displayed an increase." (PMID 36641471, 2023). "TGF-β promotes the EMT via the SMAD2/3 pathway, and MMP-9 is a TGF-β target gene that promotes tumor invasion." (PMID 37524814, 2023). "Our results confirmed the roles of β‐catenin, SMAD2, and SMAD3 in promoting EMT, and identified the roles of tumor suppressor MYBBP1A, NKRF, and MYPOP in repressing the EMT process." (PMID 37566765, 2023). "Collectively, we proved that pirfenidone blocks TGF-β1-induced fibrotic changes via the inhibition of the canonical Smad2/3 signaling pathway as well as the reduction in CEMIP expression levels, thus ameliorating the tumor mechano-environment." (PMID 36639658, 2023). "In line with the high expression of TRIM9, the protein level of CEACAM6, Smad2/3 and MMP2 were upregulated in TRIM9 overexpressed tumor tissues." (PMID 37249822, 2023). "Online miRNA target prediction database (Targetscan) was used to identify potential miR-371b-5p target genes, we identified both probable miR-371b-5p binding sites in Smad2 and LEF1, two positive regulators of tumor progression." (PMID 37106379, 2023). "Increasing evidence has suggested that Smad2/3 signaling regulates the basal and TGF-β-induced MMPs expression to facilitate tumor progression." (PMID 37249822, 2023).
tumor (continued). "Mechanically, tumor cells educated neutrophils via TGFβ1 to produce more FAM3C through Smad2/3 signaling activation, and FAM3C promoted tumor cell EMT through JNK-ZEB1/Snail signaling pathway." (PMID 37056931, 2023). "Then, TGFβ1 binds to TGFBR1/R2 in tumor cells to activate Smad2/3 signalling to increase the expression of PAI-1, which further activates PI3K/AKTThr308, p-Bad and Bcl-2 to support tumor cell survival in circulation." (PMID 37705745, 2023). "The univariate Cox regression analysis revealed that SMAD2, SMAD3, TNM staging system, and tumor stage were independent prognostic factors in liver patients in TCGA." (PMID 37790613, 2023). "Because EMT, HIF-1α/VEGF, and PI3K/AKT signaling pathways tightly regulate tumor migration and invasion, we evaluated EMT progress by measuring the protein expression levels of Twist, E-Cadherin, and Smad2 in DLD1 cells." (PMID 35860704, 2022). "In metastatic lymph nodes, the presence of both p-Smad2 expression and c-Met expression revealed heterogeneity of HER2 expression, as in the primary tumor." (PMID 35650563, 2022). "The abnormal expression of SMAD2 can directly inhibit the activation state of the TGF-β signaling pathway, thereby freeing tumor cells from growth inhibition." (PMID 35386287, 2022). "Accordingly, we observed that exposure of tumor cells to [Zn(PipNONO)Cl] counteracted the expression of TGF-β1 and its downstream transcription factor Smad2/3, restoring the epithelial phenotype of tumor cells." (PMID 36077778, 2022). "We evaluated the effect of tumor cells, alone or in combination with [Zn(PipNONO)Cl], on the downstream transcription factors of TGF-β1 and Smad2/3." (PMID 36077778, 2022). "While Smad3 elicits pro-tumor functions by enhancing EMT, invasion and angiogenesis, Smad2 displays opposite effects in many scenarios to suppress tumor progression." (PMID 35794621, 2022). "Because of the low expression of core TβR1/2, (p-)SMAD2 and SMAD4 proteins and the correlation with worse prognosis, TGF-β pathway most likely leads to tumour inhibitory effects in AC and therefore the use of TGF-β inhibitors would not be recommended." (PMID 35756604, 2022). "Knockdown of circSMAD2 notably inhibited the expression of SMAD2 in GBC cells, and SMAD2 overexpression partially reversed the anti-tumor effect of circSMAD2 knockdown." (PMID 34727877, 2021). "The combination treatment significantly reduced the expressions of p-AKT, p-PI3K, Smad2, Smad3, p-JNK, p-ERK, and NF-κB in tumor tissues, all of which are signaling molecules involved in TGF-β1-induced EMT." (PMID 34948368, 2021). "Of which, SMAD2, PPP3CA, MAPK1, and FOS genes are known to be involved in the regulation of tumor cell proliferation and invasion." (PMID 33959508, 2021). "In late tumor stages, TGF-β1 signaling activation induces Smad2/3 phosphorylation and translocation to nucleus, thus exerting tumor EMT process, invasiveness and metastasis." (PMID 34130705, 2021). "The downregulation of the tumor promoter H19 and its target gene APOBEC3G was most significant and converged in inhibition of Smad2/TGF-β, which is involved in prevention of PDAC progression." (PMID 33669381, 2021). "In examining the dissected tumor tissues, both dipyridamole and GW4869 decreased protein contents in cyclin D1, β-catenin, YAP1, Runx2, phosphorylated Smad2/3, HMGB1, RAGE, and CD42b, except the TLR4." (PMID 33669632, 2021). "Smad2, Smad3, Smad4, and COL1A1 proteins were strongly expressed in tumor tissues from CRC patients compared with normal colon controls." (PMID 34966673, 2021). "In tumor cells, PSPC1 interacts with SMAD2/3 in the nucleus through its NOPS-coil domain in a TGFβ-dependent manner." (PMID 34359789, 2021).
tumor (continued). "In vivo, sulforaphane- or H19 or APOBEC3G siRNAs led to significantly smaller tumor xenografts with reduced expression of Ki67, APOBEC3G and phospho-Smad2." (PMID 33669381, 2021). "The present results show that the tumor tissues of TNBC mice treated with a combination of low-dose Avastin and FO with Se have significantly lower levels of Smad2/Smad3 phosphorylation, Smad4, and TMEPAI than those of mice treated with Avastin alone." (PMID 33805447, 2021). "Inhibition of αvβ3 by indomethacin treatment blocks TGFβ/SMAD2/SMAD3 signalling and increases anti‐tumour immune responses in a humanized mouse model." (PMID 34709754, 2021). "There is emerging evidence supporting the role of HOXB9 as a promoter of tumour invasion and metastasis by activating the EMT process through important pathways such as the TGF-β1/Smad2/Slug signalling pathway." (PMID 34948228, 2021). "As shown, the levels of lnc-UTGF, SMAD2, and SMAD4 were significantly higher in HCC tissues compared with the matched adjacent non-tumor liver tissues." (PMID 34785655, 2021). "For 125 tissue samples (69%), a high percentage of pSMAD2-positive tumor cell nuclei was identified and ITGAV and phospho-SMAD2 staining intensities were positively correlated (P = 0.014)." (PMID 34174926, 2021). "In human colorectal tissue and tumor cells, a direct comparison of tumor cells between metastasis and non-metastasis tumors by GSVA analysis revealed that PTEN pathway, SMAD2 pathway, FGFR4 pathway, and JAK pathway were the enriched signatures in tumor cells." (PMID 34026600, 2021). "Under the TGF-β signal transduction pathway, the SMAD2 and SMAD3 genes were found to be critical intracellular mediators, even reflecting tumor-inhibitory or tumor-inducing effects." (PMID 34579396, 2021). "Our study revealed a novel mechanism by which miR-3613-3p regulates SMAD2/EZH2 network in TNBC and demonstrated that miR-3613-3p functions as a tumor-suppressive miRNA in TNBC." (PMID 33330073, 2020). "Smad2/3 are the key transducers of the termed transforming growth factor-β (TGF-β) signaling pathway, whose activation promotes tumor growth including CC." (PMID 32423468, 2020). "EMP3 expression was found to be correlated with the activation of TGF-β/Smad2/3 signaling by interaction with TGFBR2, which resulted in TGF-β stimulated gene expression and tumor cell proliferation." (PMID 32857809, 2020). "In the tumor microenvironment, TGF-β signaling affects tumor progression by phosphorylating or interacting with numerous factors, including Smad2/3/4, Ras/MAPK/ERK, and PI3K/AKT signaling, depending on the cell context." (PMID 31548612, 2020). "The results validated that down-regulation of HDAC3 or TGIF1, or up-regulation of miR-296-3p resulted in suppressed tumor growth, elevated apoptosis rate and inhibited TGF-β1, Smad2 and Smad3 expression." (PMID 33203425, 2020). "The blocking of Slit2/Robo1 signaling by R5 attenuated TGF-β1 phosphorylation of Smad2 and Smad3 in Lovo cells, SW480 cells, and tumor tissues of ApcMin+ mice compared with mIgG-treated groups." (PMID 31242633, 2019). "Increased expression of pSMAD2/3 (phosphorylated SMAD2 and SMAD3) and PAI-1 (plasminogen activator, TGF-β1 target gene) was observed in more differentiated ccRCC tumor samples and correlated with a larger tumor size and lower patient survival rate." (PMID 31842336, 2019). "Since tumor angiogenesis is dependent on tip cell formation, which is essentially modulated by the interaction of Notch and NRP1-mediated Smad2/3 signaling, inhibition of NRP1 is an attractive target for restraining tumor angiogenesis." (PMID 30717262, 2019). "TGF-β/Smad2/3 signaling was reported to induce EMT, which was correlated to tumor progression and metastasis." (PMID 30728352, 2019). "The results indicated that both TGFβ1 receptor and Smad2 were involved in the process that MSCs facilitated the expression of FAPa and MMP9 in VX2 tumor tissue." (PMID 31528217, 2019).
tumor (continued). "The results indicated that both TGFβ1 receptor and Smad2 were involved in the process that MSCs facilitated the expression of TGFβ1 and EGF in VX2 tumor tissue." (PMID 31528217, 2019). "The tumor lysates of five TNBC patients (BC1-BC5) and four normal/benign tissues (N1-N4) showed similar differences in Smad2 and Smad3 protein expression levels in tumors vs normal/benign tissues as was noted in established cell lines." (PMID 31798766, 2019). "The closely clustered SMAD2/3 Nuclear Pathway contains SMAD3 which regulates expression of angiogenic molecules in tumor cells and vascularization in tumor lesions." (PMID 29554099, 2018). "We then explored the role of miR-655 in PC cells, which demonstrated the tumor suppressive role of miR-665 via targeting TGFBR1 and TGFBR2 by regulating SMAD2/SMAD3 pathway." (PMID 29899418, 2018). "For example, miR-27a was found to be downregulated and showed tumor-suppressive functions in CRC, targeting Stat3 and Smad2; in other studies, this same miR was found to be upregulated and showed oncogenic functions in CRC." (PMID 28902152, 2017). "In general, TGF-β conveys signals through phosphorylation of Smad2/3, but it also can transduce signals via Ras/ERK1/2, PI3 K, p38, and RhoA pathways, the latter processes augmenting its tumor promoting activity." (PMID 28959141, 2017). "There are many validated miRNA-148a’s target genes contributing to the tumor metastatic behavior, including MMP7, ROCK1, SMAD2, Met and cholecystokinin B receptor (CCK-BR)." (PMID 28199399, 2017). "The tumor suppressor genes PIK3C3 on chr18q12.3 and SMAD2 on chr18q21.1, which affected the TGF-β pathway, were reported to be related to metastasis." (PMID 29169336, 2017). "To this end, we measured the protein levels of cyclin D1, phospho-Smad2/3, and Smad4 in 40 of HCC tumor tissues." (PMID 28415588, 2017). "In epithelial cells and during tumor initiation, TGF-β acts as a tumor suppressor by inhibiting the growth of malignant cells via canonical SMAD2/3 signaling activity." (PMID 28067804, 2017). "On the other hand, pathways driven by the transcription factors mediating stress responses or tumor suppression, including GATA, SMAD2/3/4 and MEF2 were dowregulated." (PMID 26993100, 2016). "FHL1 was identified functionally interacted with oestrogen receptors (ERs), Smad2/3/4, HIF-1, human T-cell leukemia virus type 1 Tax oncoprotein and ZO-1 in various cancer types, suggesting that its functions as either a tumor suppressor or oncoprotein." (PMID 26908444, 2016). "RHOA, SMAD2, SMAD4, SMAD5, SMAD6, BMPR1A, SMAD7 and MYC-, which thereby emerge as candidate genes to play an important role in CRC tumor metastasis." (PMID 27662660, 2016). "In TIL, SMAD2/3 and NFAT pathways cooperate downstream of TGF-β signaling to enhance anti-tumor immunity by increasing CD103 expression." (PMID 26393659, 2015). "More specifically, when PEAK1 is upregulated in the presence of fibronectin, TGFβ signaling can co-regulate Smad2/3 and MAPK signaling to promote EMT, tumor cell migration/proliferation and cancer metastasis." (PMID 26267863, 2015). "In contrast, the phosphorylation of both Smad2 and Smad4 was significantly reduced in the tumors treated with the inhibitor (OVA + tumor + Inh), indicating that blocking TβRI inhibits the TGF-β signaling cascade." (PMID 26076663, 2015). "A total of 16 tumor tissue arrays were analyzed for TGF-Δ1 and -2 expression as well as for Smad2/3 phosphorylation, reflective of pathway activation." (PMID 26450853, 2015). "In this system, Foxp1 blocks anti-tumor function of murine TIL through transcriptional control of AP-1 complex formation, interacts in the nucleus with SMAD2/3, and is required for inhibition of CD8+ T cell function by TGF-β." (PMID 26393659, 2015). "The SMAD2 and SMAD3 transcription factors lie at the core of the transforming growth factor (TGF) pathway, which promotes tumor invasion and Epithelial-Mesenchymal Transition (EMT)." (PMID 26356815, 2015).